RNU6-570P (RNA, U6 small nuclear 570, pseudogene)
Gene: Small nuclear RNA gene on chromosome 1 (200,054,061 to 200,054,165, forward strand). Ensembl gene ENSG00000252860.
Homologues: Orthologues: chimpanzee U6 (99% identical), macaque U6 (92% identical), pig U6 (65% identical), rat LOC120095373 (65% identical), mouse Gm25867 (63% identical). Paralogues in human: RNU6-1209P (82% identical), RNU6-1287P (81% identical), RNU6-204P (81% identical), RNU6-188P (80% identical), RNU6-23P (80% identical), RNU6-797P (80% identical), RNU6-1154P (79% identical), RNU6-1175P (79% identical), RNU6-11P (79% identical), RNU6-1309P (79% identical), RNU6-196P (79% identical), RNU6-211P (79% identical), and 1283 more.